MEF2C (myocyte enhancer factor 2C)
Diseases named in the same sentence as MEF2C in open-access papers (continued):
Sharing a sentence is not in itself a finding about the gene and the disease.
infection (15 papers, 2011 to 2024). The state of being infected such as from the introduction of a foreign agent such as serum, vaccine, antigenic substance or organism. "However, infection of Erk5–/– embryos with an adenovirus encoding a constitutively active Mef2c was only able to partially protect endothelial cells from apoptosis, suggesting the existence of additional effectors downstream of ERK5 that regulate apoptosis." (PMID 36980305, 2023). "Only the Mef2c-Gata4-Tbx5 (MGT) and Mef2c-Tbx5-Gata4 (MTG) constructs, which have Mef2c in the first position, increase reprogramming efficiency compared to infection with three separate Gata4, Mef2c, and Tbx5 viruses." (PMID 28389873, 2017). "After sorting, MEF2C-expressing cells (40–65% positive for infection marker) were cultured in the same B cell differentiation condition with or without drug treatments." (PMID 26900922, 2016). "Given that MEF2C is also a known cell-survival factor and that smaller-than-normal neurospheres were observed after infection with lenti-shMEF2C-1 virus, we initially quantified cell death using the TUNEL assay at different time points after lenti-infection." (PMID 21901155, 2011). "Moreover, the upregulation of IRS1 and MEF2c mRNAs in SARS-CoV-ΔE versus WT infection correlated with miRNA-145a and 223 downregulation, respectively." (PMID 35229638, 2022). "However, for MICFs, only about 0.1% cells were induced into cardiomyocyte-like cells after the infection of Gata4, Mef2c, and Tbx5." (PMID 33718351, 2021). "Among the GMT, Mef2c seems most rapidly targeted into nucleus, whereas Gata4 and Tbx5 were slower and observed in both the cytosol and nucleus by 3 hours of infection, however, by 4 hours of the infection time, most of injected proteins were localized into the nucleus." (PMID 26449528, 2015). "Infection with SIV results in damaged myoblast differentiation, with concomitant reductions in muscle-specific miRNA-206 and MEF2C expression levels." (PMID 37962454, 2024). "Only 3 (IRS1, MEF2c, and GZMB) out of 29 miRNA predicted mRNA targets showed statistically significant expression changes (FC > 2; FDR < 0.05) in SARS-CoV-WT versus ΔE infection." (PMID 35229638, 2022). "In our experimental conditions, the infection of RNVC with adMek1ca provokes a 60% decrease in Myh6, Mef2c, and Gata4 mRNA expression and a 40% decrease in Srf mRNA expression." (PMID 30206251, 2018). "In up-regulated genes of head kidney samples, 2 genes respond to infection by D. pseudospathaceum-clone I (HYAL2, PRF1), 3 to clone XII (RGCC, CYP27B1, CCR9) and 6 to the clone mix treatment (ITGA5, SIX1, ATP1B3, MEF2C, MLF1, MYLPF)." (PMID 25254967, 2014). "We found a significant reduction in both MEF2C and MAP2 mRNA expression and protein levels after infection with lenti-shMEF2Cs." (PMID 21901155, 2011). "These signaling pathways showed that, after LPS infection, several DEGs were mainly related to immune function, such as up-regulated expression of CCL5, IL8, NFKBIA, TRAF3, and TNFAIP3, and down-regulated expression of MEF2C, MAP2K6, TLR1, TLR2, and IRF5." (PMID 34067819, 2021). "At 14 days post infection (dpi, during the NPC stage), lenti-shMEF2C-1—infected cells displayed an ∼2-fold higher level of cell death than scrambled control-infected cells or lenti-shMEF2C-2—infected cells, consistent with an early effect of MEF2C on cell viability." (PMID 21901155, 2011). "Consistent with the data from cultured cells, infection with Ad-PIMT Ser298Asp but not Ad-PIMT Ser298Ala suppressed GLUT4, MEF2A, MEF2D expression while up-regulating PGC1-α, HDAC5 and MEF2C expression in the rat skeletal muscle tissue." (PMID 26468734, 2015).
psychiatric disorder (7 papers, 2019 to 2023). A disorder characterized by behavioral and/or psychological abnormalities, often accompanied by physical symptoms. "These included the MHC region; DRD2, the dopamine D2 receptor involved in mood and emotion; MEF2C, a gene that regulates synaptic function; TCF4, a regulator of prefrontal neuronal excitability and RBFOX1, a gene splicing regulator that has also been implicated in other psychiatric disorders." (PMID 31576797, 2020).
neurological disorders (6 papers, 2018 to 2025). "In this study, we examined the role of Mef2c, a transcription factor implicated in a number of neurological disorders through characterization of the expression and functional relevance of Mef2c in the developing cerebellar cortex." (PMID 30276662, 2019). "The transcription factor myocyte enhancer factor 2c (Mef2c) has been identified in human genetic analysis as a susceptibility gene for a number of neurological disorders." (PMID 30276662, 2019). "Yet very few studies have investigated the role of MEF2C in microglia at homeostasis and in developmental or neurological disorders." (PMID 41125877, 2025). "Together, these studies reveal mechanisms by which reduced microglial MEF2C could contribute to the development of neurological diseases." (PMID 41125877, 2025).
neurodegenerative disease (5 papers, 2020 to 2025). A disorder of the central nervous system characterized by gradual and progressive loss of neural tissue and neurologic function. "To assess microglial function in a neurodegenerative disease-specific context, we measured the phagocytosis and migration capacity of MEF2C-deficient microglia toward disease-relevant stimuli." (PMID 41125877, 2025). "Our result is consistent with previous studies that suggested loss of MEF2C function might contribute to the increased sensitivity of microglia to immune stimuli, as commonly observed in neurodegenerative diseases such as AD47." (PMID 33257653, 2020). "Given that AD is a neurodegenerative disease with a chronic pro-inflammatory state, downregulation of MEF2C expression may contribute to exaggerated pro-inflammatory conditions of the disease." (PMID 34103633, 2021). "Apparently, LRRN3 may be involved in the development of neurodegenerative processes in PD, while the MEF2C and SLC22A4 genes might be involved in the development of general compensatory processes typical for various neurodegenerative diseases." (PMID 39061965, 2024).
cardiac disease (4 papers, 2009 to 2025). "Collectively, the findings of this study provide new evidence of the interaction with SENP1 promoting LLPS in cells, especially in cardiac disease, solving a puzzle regarding the regulation mechanism of MEF2C stability." (PMID 40341856, 2025). "By combining our present findings on SENP1 and MEF2C deSUMOylation in protecting against ICM, it is highly likely that the modulation of the SUMO system for a selective transcription factor within cardiomyocytes is critical in the pathogenesis of cardiac disease." (PMID 40341856, 2025).
retinopathy (4 papers, 2014 to 2024). "Mef2c ablation in retinal endothelial cells enhanced cellular resistance to hypoxia induced retinopathy, and Mef2c mediated the process of activation induced cell death in macrophages with the stimulation of lipopolysaccharide." (PMID 39648651, 2024). "Finally, further evidence for an endothelial role of MEF2C in vivo is provided by the use of recently bred mice with endothelial-specific Mef2c ablation in a model of oxygen-induced retinopathy." (PMID 24988463, 2014).
cardiovascular diseases (3 papers, 2010 to 2023). "The mRNA expression of MEF2C, encoding a critical transcription factor involved in heart development and many cardiovascular diseases, was tested by RT‐PCR MEF2C expression was higher in the alcohol‐treated than in the control group (P < .05)." (PMID 31746096, 2020).
adenocarcinoma (2 papers, 2024). A common cancer characterized by the presence of malignant glandular cells. "MSA was previously grouped as “adenocarcinoma, not otherwise specified” (NOS) and classified as a unique pathologic entity by recognition of recurrent MEF2C::SS18 fusion." (PMID 38982505, 2024).
genetic disorder (2 papers, 2024 to 2025). "Mutations in the MEF2C gene, including microdeletions, missense, or nonsense mutations, have been linked to a rare genetic disorder known as MEF2C haploinsufficiency syndrome." (PMID 39259737, 2024).
myopathies (2 papers, 2009 to 2023). "Interestingly, the transcription factor MEF2C was found to be down-regulated at both the mRNA and protein levels in PrPC-mediated myopathy." (PMID 19400950, 2009). "Therefore, Mef2c activation is likely specific for certain myopathies, such as EDMD." (PMID 37395273, 2023). "We did not observe an induction of Mef2c expression in other myopathy models, indicating that Mef2c activation is not a general myopathic response." (PMID 37395273, 2023).
brain disorder (1 paper, 2025). A disease affecting the brain or part of the brain. "However, it is not known whether there is a casual relationship between the enhancer mutation of MEF2C gene and the onset of brain disorders." (PMID 39920775, 2025).
hematologic cancers (1 paper, 2025). "MEF2C (Myocyte Enhancer Factor 2 C) gene is an oncogene implicated to drive hematologic cancers." (PMID 40176070, 2025).
MEF2C also shares sentences with these, for which no sentence is quoted: Obesity (4 papers); bipolar disorder (3); diffuse large B-cell lymphoma (3); fibrosis (3); age-related hearing loss (2); Cerebral ischemia (2); cerebral malformation (2); cognitive disorder (2); coronary artery disease (2); metabolic disease (2); microcephaly (2); pancreatic adenocarcinoma (2); pulmonary hypertension (2); acute B-lymphoblastic leukemia (1); alcohol dependence (1); alveolar rhabdomyosarcoma (1); anemia (1); aortic valve disease (1); Atrophy (1); attention deficit-hyperactivity disorder (1); autosomal dominant mental retardation 20 (1); AV block (1); B-Cell CLL (1); bacterial infection (1); basal cell carcinoma (1); behavioral variant frontotemporal dementia (1); Chorea (1); chronic heart failure (1); COVID-19 (1); dependence (1).
A further 68 diseases each share a sentence with MEF2C in 1 paper.